Y_RNA (Y RNA )
Gene: Miscellaneous RNA gene on chromosome 4 (37,699,895 to 37,700,002, reverse strand). Ensembl gene ENSG00000207075.
Homologues: Orthologues: chimpanzee Y_RNA (100% identical), macaque Y_RNA (96% identical). Paralogues in human: Y_RNA (82% identical), RNY1 (80% identical), Y_RNA (80% identical), Y_RNA (79% identical), RNY1P11 (78% identical), RNY1P8 (78% identical), Y_RNA (78% identical), Y_RNA (77% identical), Y_RNA (76% identical), Y_RNA (75% identical), RNY1P10 (74% identical), RNY1P7 (74% identical), and 92 more.